KIFAP3 (kinesin associated protein 3)
Description:
Involved in tethering the chromosomes to the spindle pole and in chromosome movement. Binds to the tail domain of the KIF3A/KIF3B heterodimer to form a heterotrimeric KIF3 complex and may regulate the membrane binding of this complex (By similarity).
Synonyms: KAP-3; KAP3; SMAP; FLA3; KAP-1; Smg-GDS; dJ190I16.1
Tractability: PROTAC: ubiquitination databases record sites on it; its protein half-life has been measured.
Gene: Protein-coding gene on chromosome 1 (169,921,326 to 170,085,208, reverse strand). Ensembl gene ENSG00000075945.
Subcellular location (Human Protein Atlas): Basal body; Microtubules; Nucleoplasm
Pathways (Reactome):
Vesicle-mediated transport: COPI-dependent Golgi-to-ER retrograde traffic; Translocation of SLC2A4 (GLUT4) to the plasma membrane
Hemostasis: Kinesins
Immune System: MHC class II antigen presentation
Organelle biogenesis and maintenance: Intraflagellar transport
Gene Ontology:
Molecular function: kinesin binding; protein binding; protein phosphatase binding; intraciliary transport particle B binding
Biological process: cilium organization; microtubule-based movement; microtubule-based process; plus-end-directed vesicle transport along microtubule; protein-containing complex assembly; signal transduction; anterograde dendritic transport of neurotransmitter receptor complex
Cellular component: centrosome; condensed nuclear chromosome; kinesin II complex; microtubule cytoskeleton; spindle microtubule; axoneme; ciliary tip; ciliary transition zone; cilium; cytosol; endoplasmic reticulum; ciliary basal body; dendrite cytoplasm; glutamatergic synapse; Golgi apparatus; kinesin complex; periciliary membrane compartment; photoreceptor connecting cilium; photoreceptor inner segment; photoreceptor outer segment; postsynapse
Genetic constraint (gnomAD): Loss-of-function variants: 20 observed, 28.89 expected, observed/expected ratio (o/e) 0.69, 90% interval 0.49 to 1.01. The upper end of that interval is the gene's LOEUF score, 1.01, which puts it in group 4 of 6, group 1 being the genes least tolerant of losing a copy. Missense variants: 233 observed, 293.33 expected, observed/expected ratio (o/e) 0.79, 90% interval 0.71 to 0.88. Synonymous variants: 98 observed, 98.53 expected, observed/expected ratio (o/e) 0.99, 90% interval 0.84 to 1.18.
Homologues: Orthologues: chimpanzee KIFAP3 (100% identical), macaque KIFAP3 (99% identical), rabbit KIFAP3 (99% identical), pig KIFAP3 (98% identical), mouse Kifap3 (98% identical), rat Kifap3 (97% identical), dog KIFAP3 (95% identical), tropical clawed frog kifap3 (89% identical), zebrafish kifap3a (81% identical), zebrafish kifap3b (76% identical), Drosophila melanogaster Kap3 (47% identical), Caenorhabditis elegans kap-1 (33% identical).
Diseases named in the same sentence as KIFAP3 in open-access papers:
KIFAP3 is named in the same sentence as 21 diseases in open-access papers, as found by Europe PMC text mining. Sharing a sentence is not in itself a finding about the gene and the disease. The quoted sentences say what the papers report.
endometriosis (2 papers, 2015 to 2025). The growth of functional endometrial tissue in anatomic sites outside the uterine body. "The endometriosis risk allele T of rs560584 (OR = 1.14 (1.07–1.22),P = 1.42 × 10−4) was associatedwith lower WHRadjBMI (β = −0.021,P = 1.47 × 10−5), and located inan intergenic region 46 kb downstream of KIFAP3(Kinesin-associated protein 3)." (PMID 25296917, 2015). "In addition to 7p15.2, weidentify four more variants with statistically significant evidence of involvement inboth endometriosis and WHRadjBMI (in/near KIFAP3,CAB39L, WNT4, GRB14); two ofthese, KIFAP3 and CAB39L, are novel associationsfor both traits." (PMID 25296917, 2015).
breast carcinoma (1 paper, 2021). "The KIFAP3 gene is highly expressed at the mRNA and protein levels in breast cancer." (PMID 34109184, 2021).
ciliopathy (1 paper, 2019). A genetic disorder of the cellular cilia or the cilia anchoring structures, the basal bodies, or of ciliary function. "The GO/EMAPA enrichment profiles of these mutant lines clustered together with a sixth gene, the kinesin 2 complex member Kifap3, which was not previously implicated in ciliopathies." (PMID 31243271, 2019).
Coronary disease (1 paper, 2015). "Besides, the organ system distribution similarity of phenotypes from mice harboring genetically modified forms of KIFAP3 (Kinesin-Associated Protein 3) and symptoms of coronary diseases may indicate the possible role of this kinesin in Coronary disease." (PMID 25313158, 2015). "For example, using the Multi-search query ‘Coronary disease|Sodium Chloride|KIFAP3’, the disease Coronary disease can be compared with the drug Sodium Chloride and the gene coding for Kinesin-Associated Protein 3 (KIFAP3)." (PMID 25313158, 2015).
motor neuron disease (1 paper, 2019). "This ties into other findings in epigenetic research such as the identification of “KIFAP3 (Kinesin-associated protein 3) which prolongs the lifespan of motor neuron disease sufferers (dubbed the “hero gene”)." (PMID 30971978, 2019).
ovarian carcinoma (1 paper, 2021). A malignant neoplasm originating from the surface ovarian epithelium. "Eight immune factors (IFT57, MAL, ANXA4, SCRN1, LTBR, KIFAP3, HSPA5, and LTN1) were positively correlated with poor prognosis of ovarian cancer, whereas six immune factors (PSMB9, FOXJ1, CTSH, MIF, CTSD, and PSMB8) were negatively correlated with poor prognosis of ovarian cancer." (PMID 34109184, 2021).
renal fibrosis (1 paper, 2024). A final common manifestation of a wide variety of chronic kidney diseases characterized by glomerulosclerosis and tubulointerstitial fibrosis. "Overexpression of KIFAP3-5:1 improved renal fibrosis in db/db mice and rescued epithelial-mesenchymal transition of high glucose cultured renal tubular epithelial cells." (PMID 38869718, 2024).
situs inversus (1 paper, 2019). A congenital condition in which there is complete right-to-left reversal of the position of the major thoracic and abdominal organs (that is, they are arranged in a mirror image of the normal positioning). "We identified two additional lines, Kif3b and Kifap3, that showed similar profiles and have morphological phenotypes such as polydactyly and situs inversus." (PMID 31243271, 2019).
KIFAP3 also shares sentences with these, for which no sentence is quoted: tumor (3 papers); cancer (2); adenocarcinoma (1); basal cell carcinoma (1); diabetic nephropathy (1); Esophageal Carcinoma (1); neuroblastoma (1); polydactyly (1); signet ring cell carcinoma of (1); tubular adenocarcinoma (1); type 2 diabetes mellitus (1); venous thromboembolism (1); viral infection (1).